KAT2A (lysine acetyltransferase 2A)
Diseases named in the same sentence as KAT2A in open-access papers (continued):
Sharing a sentence is not in itself a finding about the gene and the disease.
osteoarthritis (1 paper, 2023). A noninflammatory degenerative joint disease occurring chiefly in older persons, characterized by degeneration of the articular cartilage, hypertrophy of bone at the margins and changes in the synovial membrane. "Further analysis of KAT2A expression in synovial tissues from osteoarthritis (OA) and RA samples by immunohistochemical (IHC) directly confirmed the increased KAT2A expression in inflamed knee joints from RA patients." (PMID 37313329, 2023).
preleukemia (1 paper, 2022). "Loss of Kat2a enhances transcriptional variability of ribosome biosynthetic programs and transiently accelerates preleukemia." (PMID 35921412, 2022). "By combining single-cell RNA sequencing of preleukemia with functional analysis of transformation, we show that Kat2a loss results in global variegation of cell identity and accumulation of preleukemic cells." (PMID 35921412, 2022). "This association suggests that loss of KAT2A activity may contribute to progression of preleukemia to overt AML." (PMID 35921412, 2022). "We asked whether similar mechanisms were at play in preleukemia progression facilitated by Kat2a loss." (PMID 35921412, 2022). "GMP-to-PLP transition is also accompanied by enhanced transcriptional variability, supporting the notion that Kat2a loss may facilitate preleukemia progression through enhanced transcriptional noise." (PMID 35921412, 2022). "To investigate this, we initiated preleukemia in mouse cells with enhanced transcriptional variability due to conditional disruption of the histone lysine acetyltransferase gene Kat2a." (PMID 35921412, 2022).
prostate adenocarcinoma (1 paper, 2017). "We have highlighted known and novel drivers of prostate adenocarcinoma, suggesting further investigation into the role of KAT2A and TRIM28 in carcinogenesis." (PMID 28592290, 2017).
prostate tumours (1 paper, 2021). "Therefore, we hypothesised that KAT2A might play a critical role in the resistance of prostate tumours to hormonal treatment." (PMID 34381019, 2021).
psychosis (1 paper, 2019). "Furthermore, in MDD patients with psychosis, the mRNA level of UBE2A and KAT2A was increased (by 53 and 43%, respectively; p < 0.05) compared to controls." (PMID 30377985, 2019).
renal carcinoma (1 paper, 2023). A carcinoma arising from the epithelium of the renal parenchyma or the renal pelvis. "Specifically, KAT2A upregulation associates with worse patient outcomes in several cancers, including breast, lung, colon, and renal cancers." (PMID 36674511, 2023). "In renal cancer, KAT2A promotes tumor growth and accelerates the metastatic phenotype of cancer cells by regulating glycolytic metabolism through MCT1 upregulation." (PMID 36674511, 2023).
sarcopenia (1 paper, 2025). Progressive decline in muscle mass due to aging which results in decreased functional capacity of muscles. "Identifying these 13 ERSRCGs including FOXO1, KAT2A, and CTH brings attention to the central contribution of ER stress in the development of IPF and sarcopenia." (PMID 41325398, 2025). "KAT2A, CTNNBIP1, GABARAPL1, SEC31A, the expression of IDI1 was highly significantly elevated (p-value < 0.01) in both the Sarcopenia and Control groups in the Sarcopenia dataset GSE8479." (PMID 41325398, 2025).
urothelial carcinoma (1 paper, 2023). A malignant neoplasm derived from the transitional epithelium of the urinary tract (urinary bladder, ureter, urethra, or renal pelvis). "KAT2A is markedly overexpressed in urothelial carcinoma, and KAT2A knockdown can inhibit the progression of urothelial carcinoma." (PMID 38058677, 2023).
xeroderma pigmentosum (1 paper, 2019). Xeroderma pigmentosum (XP) is a rare genodermatosis characterized by extreme sensitivity to ultraviolet (UV)-induced changes in the skin and eyes, and multiple skin cancers. "Here the authors show that TFIIH interacts with the histone acetyl transferase KAT2A and recruits the ATAC/hSAGA complexes to chromatin; and that loss of xeroderma pigmentosum group B (XPB) function results in chromatin decondensation and increased gene expression through activation of KAT2A." (PMID 30894545, 2019).
tumor (61 papers, 2017 to 2026). "Together, these results suggest that KAT2A deficiency reduces tumor growth and improves survival in vivo." (PMID 40140561, 2025). "Given the functional role of KAT2A demonstrated in vitro, we sought to validate the effect of KAT2A deficiency on tumor growth in an in vivo setting." (PMID 40140561, 2025). "The combined inhibition of specific kinases, e.g., HER4 and KAT2A caused significant loss of tumor lipogenesis program leading to suppression of tumor-derived androgen, indicating its potential as a therapeutic strategy to overcome abiraterone-resistant CRPCs." (PMID 37296155, 2023). "KAT2A has been implicated in oncogenic processes and tumor progression." (PMID 41225436, 2025). "Furthermore, statistical analyses demonstrated significant associations between KAT2A expression and patient demographics (sex), tumor localization, and overall survival rates, suggesting its potential role as a prognostic indicator." (PMID 41225436, 2025). "Some recent publications have highlighted its potential oncogenic role as a chromatin modifier implicated in tumorigenesis and tumor progression, while other research suggested that KAT2A/2B may control genome stability." (PMID 40743051, 2025). "This post-translational modification enhanced SERPINE2 protein stability, and SERPINE2 overexpression effectively reversed the tumor-suppressive effects induced by KAT2A silencing." (PMID 41968399, 2026). "KAT2A is a major regulator of protein and histone acetylation in cancers highlighting as a central hub of tumor development and progression." (PMID 41826695, 2026). "In turn, we identified STAT3 as a palmitate responsive regulator of KAT2A expression in tumor spheroids and lung metastases." (PMID 41826695, 2026). "This study aimed to investigate the role of KAT2A in RCC and elucidate the underlying molecular mechanism by which it promotes tumor progression." (PMID 41968399, 2026). "Aberrant overexpression of KAT2A has been documented in multiple malignancies, where it correlates with aggressive tumor phenotypes and malignant biological behaviors." (PMID 41225436, 2025). "α-KGDHC can provide succinyl coenzyme A (succinyl-CoA) to succinyltransferase lysine acetyltransferase 2A (KAT2A), promoting the succinylation of histone H3, which leads to tumor cell proliferation and tumor formation." (PMID 39781339, 2025). "KAT2A and the alpha-KGDH complex are both tightly linked to gene expression and tumor cell proliferation." (PMID 40865948, 2025). "Consistent with prior observations, all four datasets confirmed significantly upregulated KAT2A expression in tumor tissues versus normal controls." (PMID 41225436, 2025). "Extensive experimental validation is therefore required to fully elucidate the impact of KAT2A on the tumor immune landscape." (PMID 41225436, 2025). "The results revealed that KAT2A was significantly upregulated in LUAD tumor tissues compared with adjacent normal tissues." (PMID 41225436, 2025). "These correlations implicate KAT2A in both tumor progression mechanisms and clinical outcome prediction for LUAD patients." (PMID 41225436, 2025). "This knowledge gap necessitated further mechanistic exploration of KAT2A’s tumor-promoting functions in LUAD." (PMID 41225436, 2025). "Tumor size, volume, and weight were significantly reduced in mice with KAT2A knockdown compared with control groups." (PMID 41225436, 2025). "Although our findings in mouse models provide valuable insights, validation in human‐derived dysplastic and OSCC lesions is crucial to confirm the role of such histones and the KAT2A gene in developing such a tumor." (PMID 40928052, 2025). "Both in vitro and in vivo experiments demonstrated that KAT2A knockdown significantly suppressed tumor cell proliferation and immune evasion mechanisms, induced apoptosis, and inhibited tumor growth." (PMID 41225436, 2025). "Recent research has highlighted the potential role of KAT2A in oncogenic transformation and tumor progression." (PMID 41225436, 2025).
tumor (continued). "The results showed that AS-IV reduced tumor size and weight compared with the control group, while KAT2A overexpression reversed the effects induced by AS-IV." (PMID 38835015, 2024). "After treatment with AS-IV, the tumor cells exhibited a large necrotic region and were stained darker, while the results were reversed after KAT2A overexpression." (PMID 38835015, 2024). "In tumor-bearing mice, AS-IV suppressed tumor growth though inhibiting KAT2A-mediated succinylation of PGAM1." (PMID 38835015, 2024). "KAT2A-mediated H3-K79succ regulates gene expression and β-catenin stability in tumor cells, contributing to tumor cell proliferation and invasion." (PMID 38882606, 2024). "KAT2A regulated multiple biological events and played a vital role in tumor initiation and progression." (PMID 38058677, 2023). "Inhibition of nuclear entrance of the KGDHC complex or expression of the KAT2A mutant with low binding affinity for succinyl-CoA reduces gene expression and inhibits tumor cell proliferation and glioma growth in mice." (PMID 36293260, 2022). "If the α-KGDH complex is blocked from entering the nucleus or KAT2A protein expression is inhibited, the expression of downstream target genes can be reduced, thus inhibiting tumor growth." (PMID 34050894, 2022). "Lastly, knockdown of MCT1 significantly impeded KAT2A-induced RCC growth in subcutaneous tumor models, as quantified by serial tumor volumes." (PMID 34268311, 2021). "The succinyltransferase activity of KAT2A is essential for histone succinylation and indispensable for tumor growth." (PMID 34268311, 2021). "To further figure out the underlying mechanisms by which KAT2A enhances RCC growth and tumor progression, we performed the RNA-seq technology to compare the differential transcriptome between KAT2A-WT and KAT2A-KO Caki-2 cells." (PMID 34268311, 2021). "We found that KAT2A was significantly higher in 530 tumor tissues than 72 normal samples with P < 0.001." (PMID 34268311, 2021). "Correlation analysis was then conducted and suggested that KAT2A expression levels were positively associated with the clinical risk factors based on the TCGA-KIRC cohort, including pathological stages, tumor grades, or TNM stages." (PMID 34268311, 2021). "We confirmed these findings via immunohistochemistry (IHC) in the RCC tumor samples from our hospital, in which immunostaining scores of KAT2A was notably higher in the advanced tumor samples than low-grade tumors or normal tissues." (PMID 34268311, 2021). "Lastly, multivariate Cox regression analysis was conducted to suggest that KAT2A expression level, age, pathological stages, tumor grades, and T stage were all independent factors and associated with a 5-year survival of RCC patients." (PMID 34268311, 2021). "We mined the GEO database and found that KAT2A expression was up-regulated in PC tumours compared to levels in the adjacent tissues." (PMID 34381019, 2021). "Inhibition of MCT1 with AZD3965 resulted in suppression of tumor growth induced by KAT2A (lysine acetyltransferase 2A, involved in the mediation of post-translational modification in histone H3)." (PMID 35011413, 2021). "α-KGDC binds to the promoter regions of lysine acetyltransferase 2A (KAT2A, also known as GCN5), and KAT2A also acts as a succinyltransferase and succinylates histone H3 on lysine 79, which facilitates histone succinylation and tumor cell proliferation." (PMID 35004688, 2021). "Consistently, the protein level of KAT2A was higher in tumour tissues than in the adjacent tissues collected from 12 patients with PC." (PMID 34381019, 2021). "In this study, we utilized the bioinformatic methods to find that chromatin modifier KAT2A was significantly high in the tumor samples than normal tissues." (PMID 34268311, 2021).
tumor (continued). "Although studies about the relationship of KAT2A‐mediated histone succinylation and diseases need further clarification, KAT2A‐mediated histone acylation has been reported to be correlated with the tumour development processes." (PMID 34160884, 2021). "The interaction between NFYC and KAT2A indicates that POU5F1 participates in tumor development through KAT2A‐mediated histone H3 succinylation." (PMID 32978904, 2020). "A high TAK1 signature very clearly separated high-ADAM12 from low-ADAM12 tumors both in lung and colon, and the TAK1 activation score was positively correlated with ADAM12 expression, and negatively correlated with KAT2A expression, in both tumor types." (PMID 30753595, 2019). "Altogether, these data agree with and extend our mechanistic data obtained in vitro, arguing that KAT2A negatively regulate ADAM12 expression in several prevalent human tumor types." (PMID 30753595, 2019). "Preventing the OGDH complex from entering the nucleus avoids nuclear generation of succinyl-CoA and the subsequent KAT2A-dependent H3 succinylation, reducing gene expression and inhibiting tumor cell proliferation and tumor growth." (PMID 31100940, 2019). "Our findings highlight the significance of the metabolic enzyme α-KGDH-coupled KAT2A complex in the regulation of gene expression, tumor cell proliferation, and tumor formation." (PMID 30109122, 2018). "Furthermore, CD8 + T cells exhibited enhanced cytotoxic activity against tumor cells in response to KAT2A depletion." (PMID 41225436, 2025). "Our data showed that KAT2A expression was positively correlated with both pyrimidine metabolism and the acetyltransferase complex, suggesting that KAT2A may influence tumor proliferation." (PMID 41225436, 2025). "ACVRL1 and KAT2A are the only two nodes with low correlation to tumor purity (FDR > 0.001)." (PMID 40228208, 2025). "To evaluate the therapeutic potential of KAT2A inhibition, we sought to induce the KAT2A knockdown after the formation of 3D spheroids, mimicking the clinical scenario in which most CRCs are diagnosed at advanced stage when complex 3D tumor structures are already established." (PMID 40140561, 2025). "Importantly, emerging evidence suggests that KAT2A participates in regulating both tumor cell proliferation and immune evasion in various cancers." (PMID 41225436, 2025). "Although there is no direct evidence that α-KGDH is involved in drug resistance, we infer that α-KGDH may contribute to MDR via KAT2A-mediated histone succinylation in tumor cells." (PMID 40612109, 2025). "Taken together, AS-IV suppressed tumor growth via inhibiting KAT2A-mediated succinylation of PGAM1." (PMID 38835015, 2024). "Finally, we established the tumor-bearing mouse model to explore the role of AS-IV and KAT2A in vivo." (PMID 38835015, 2024). "The role of KAT2A in vivo was explored using a xenografted tumor model." (PMID 38835015, 2024). "We speculated that KAT2A might promote tumor metastasis and proliferation by participating in the establishment of an immunosuppressive tumor microenvironment." (PMID 38058677, 2023). "Meanwhile, KAT2A may contribute to the construction of an immunosuppressive tumor microenvironment, which may become a target for immunotherapy to further guide clinical treatment decisions." (PMID 38058677, 2023). "The succinyltransferase ability of KAT2A is indispensible for promoting tumor growth or migration." (PMID 37415153, 2023). "Last, of all, the subcutaneous xenograft model confirmed that TRIM22 depletion led to enhanced in vivo tumor growth, which could be notably inhibited by KAT2A knockdown, as indicated by tumor volume curves and tumor weight." (PMID 37415153, 2023). "KAT2A was highly expressed in non-small-cell radiation-induced lung cancer and may promote tumor progression by upregulating E2F1 and cyclin d1." (PMID 38058677, 2023).
tumor (continued). "Besides, we also observed the elevated expression levels of KAT2A in tumor tissues across other RCC cohorts, including the ICGC-RCC cohort and GSE40435." (PMID 34268311, 2021). "The acetylation level in xenograft tumour tissues was also decreased in the KAT2A-knockdown group." (PMID 34381019, 2021). "and AZD3965 was significantly effective to suppress the tumor progression induced by KAT2A." (PMID 34268311, 2021). "The gene KAT2A had an upregulated expression in 9 tumor types." (PMID 31828117, 2019). "Expression of a succinylation-deficient, but acetylation-proficient KAT2A mutant inhibited tumor growth in mice, demonstrating that succinylation has nonredundant roles to acetylation." (PMID 31699900, 2019). "However, when we attempted this analysis using MYC-low or KAT2A-low subsets, the compartment calls were more dissimilar to both normal and tumour compartment calls than they were to each other." (PMID 28592290, 2017). "KAT2A, a histone acetyltransferase (HAT) and a member of the GCN5-related N-acetyltransferase (GNAT) superfamily, interacts with acetyl-CoA and transfers its acetyl residues to histones and is associated with gene expression, tumor formation, and tumor cell proliferation." (PMID 34149798, 2021). "However, little was investigated between KAT2A and tumor metabolism." (PMID 34268311, 2021). "Functionally, KAT2A depletion markedly inhibited RCC cell proliferation, migration, EMT, and HUVECs angiogenesis in vitro, as well as suppressed tumor growth in vivo." (PMID 41968399, 2026). "The results demonstrated that KAT2A silencing suppressed cell proliferation and immune evasion, promoted apoptosis of LUAD cells, and inhibited tumor growth in xenograft mouse models." (PMID 41225436, 2025). "Epigenetic regulation of KAT2A was further investigated, revealing that promoter methylation levels were significantly reduced in LUAD tumor tissues compared to normal tissues." (PMID 41225436, 2025). "This is consistent with a recent report that targeting KAT2A/KAT2B with a PROTAC degrader, GSK-699, suppresses NB tumor growth." (PMID 40274766, 2025). "Collectively, these findings highlight the multifaceted role of KAT2A in LUAD, involving extensive interactions with diverse genes and pathways critical to tumor biology." (PMID 41225436, 2025). "The seven genes comprising the HMR model (SUZ12, KAT2A, AURKA, BUB1, SUV39H2, UTY, and PCGF5) are critically involved in epigenetic modification, tumor progression, supporting their prognostic value in MM." (PMID 40949882, 2025). "In this study, we systematically investigated the role of KAT2A in LUAD, with particular emphasis on its impact on patient prognosis, tumor progression mechanisms, and immune microenvironment dynamics." (PMID 41225436, 2025). "We collected tumor and adjacent normal tissues from LUAD patients and assessed KAT2A expression via qPCR, Western blot, and tissue microarray analyses." (PMID 41225436, 2025). "In tumor-bearing mice, AS-IV treatment suppressed the tumor growth and the succinylation of PGAM1, while KAT2A overexpression reversed these results." (PMID 38835015, 2024). "GCN5 was overexpressed in HCC, and downregulation of KAT2A inhibits HCC cell and xenograft tumor proliferation." (PMID 38058677, 2023). "KAT2A and PPARD showed different expressions based on tumor stages and grades with favorable survival rates in patients." (PMID 36476410, 2022). "Various enzymes exhibit a high succinyltransferase activity, such as KAT2A (lysine acetyltransferase 2A) that succinylates H3K79, with a maximal affinity for gene transcription start sites, promoting tumor growth." (PMID 35631199, 2022). "From the result of correlation analysis in tumor tissue samples across 11 cancer types and cell line samples in CCLE, we found that the correlation coefficient between the two in KAT2A, E2F1, and UBE2C was 0.037–0.82." (PMID 36292703, 2022).